CCL5 (C-C motif chemokine ligand 5)
Diseases named in the same sentence as CCL5 in open-access papers (continued):
Sharing a sentence is not in itself a finding about the gene and the disease.
breast cancer (continued). "We analyzed peripheral blood and tumor tissue cells from breast cancer patients via flow cytometry to further explore the mechanism by which CCL5/CCR5 affects the progression of breast cancer." (PMID 36033472, 2022). "We found that CCL5 was positively correlated with axillary lymph node metastasis in breast cancer and that CCL5 was positively correlated with factors that predicted poor prognosis in breast cancer." (PMID 36033472, 2022). "After analyzing the data of breast cancer patients in the GEO and TCGA databases, we found that CCL5 is likely to play a tumor-promoting role through CCR5." (PMID 36033472, 2022). "Specifically, we found that miR-155 overexpression in human primary breast cancer cells significantly increased Ccl5 and Cxcl10/11 expression." (PMID 35925680, 2022). "We performed immunofluorescence staining of breast cancer tissues and found that CCL5 and CCR5 were mainly expressed in CD4+ T cells but rarely expressed in CD8+ T cells." (PMID 36033472, 2022). "Considering the function of host-derived CCL5 in breast cancer progression and tumor immunosuppression, in the present study, CCL5-deficient mice (CCL5−/−) were used to establish the 4T1 model." (PMID 35327361, 2022). "CCL2 and CCL5 play important roles in prostate cancer metastasis and drug resistance, while CCL4 is associated with the clinical characteristics of breast cancer." (PMID 33737938, 2021). "Although factors such as CCL5 that enable recruitment of TAMs to mammary tumors have been identified, the process by which recruited macrophages are educated or polarized by tumor cells is not well-understood." (PMID 34298673, 2021). "Elevated levels of CCL5 indicate poor prognosis in breast cancer, pancreatic cancer, cervical cancer, prostate cancer, ovarian cancer, and gastric cancer." (PMID 33485378, 2021). "The CCL5/CCRs axis was therefore considered to have a pivotal role in breast cancer, and we subsequently examined the relationship between CCL5/CCRs and their clinicopathological parameters." (PMID 33671956, 2021). "In breast cancer, cancer cells induce production of CCL5 (also called RANTES) from MSCs via interacting with CCR5, increasing cancer cell motility, invasion, and metastasis in vitro and in vivo." (PMID 34736460, 2021). "Analyses of clinical breast cancer data showed significant correlation between expression of CCL5 and a set of genes correspondingly regulated in macrophages by tumor EVs and CCL5 expression." (PMID 34298673, 2021). "In breast cancer, CCL5-producing Treg cells promoted metastatic progression via CCR5-expressing breast cancer cells." (PMID 34503058, 2021). "Overexpressed CCR5 or the ligand CCL5 was reported to be related with poor prognosis of multiple cancers, such as breast cancer 26, ovarian cancer 27 and cervical cancer 28, which was in line with our results." (PMID 33995630, 2021). "In particular, MSCs recruited to the breast cancer microenvironment secrete chemokine ligand 5 (CCL5) that promotes cancer cell invasion and metastasis." (PMID 33526787, 2021). "Results from a clinical study indicate that levels of CCL5 in breast cancer patients are higher than that of healthy controls." (PMID 33747948, 2021). "In breast cancer, CCL5 secreted from TAMs has been reported to contribute to tumor malignancy by promoting epithelial–mesenchymal transition (EMT) and aerobic glycolysis." (PMID 33671956, 2021). "For example, breast cancer cells enhance the expression of RANTES/CCL5 in MSCs, an event that rapidly occurs via cell–cell contact." (PMID 34680425, 2021). "The disease-free survival of patients with early breast cancer with high CCL5 expression is improved compared with that of patients with low CCL5 expression." (PMID 34218795, 2021). "Elevated CCL5 levels are correlated with progression of breast cancer as well as increasing the metastatic potential of MDA-MB-231 cells in vivo." (PMID 34602068, 2021).
breast cancer (continued). "Lactate induces the TAM phenotype, inducing CCL5 expression which promotes breast cancer cellular EMT and aerobic glycolysis via AMPK." (PMID 34631530, 2021). "Although the roles of CCL5 and its receptors on breast cancer progression have been previously examined in vitro and in vivo by several groups, the results were not always consistent." (PMID 33671956, 2021). "We and others have shown that ectopic expression of RKIP partially suppresses breast cancer lung metastasis and F4/80+ tumor macrophage infiltration by inhibiting CCL5 expression in orthotopic mouse models." (PMID 34465801, 2021). "Leronlimab reduced CCL5-induced MDA-MB-231 breast cancer cell invasion with similar efficacy as vicriviroc (855 ± 8.7, N = 8 for control vs. 520 ± 9.1 μM distance traveled, N = 9 for leronlimab, P < 0.001)." (PMID 33485378, 2021). "High expression of CCL5 has been correlated with poor prognosis in many cancers, including glioblastoma and breast cancer." (PMID 34988021, 2021). "Stromal CCL5 immunoreactivity was significantly correlated with the aggressive phenotype of breast carcinomas." (PMID 33671956, 2021). "Studies demonstrated that CCL5 is related to certain tumor cells, such as malignant melanoma cells, ovarian, prostate, and breast cancer cells." (PMID 32963529, 2020). "Serum CCL5 is higher in breast cancer patients than in healthy individuals and tends to be higher in advanced disease stages." (PMID 32630699, 2020). "The upregulated CCL5 production is responsible for the increased recruitment of macrophages into the lung, which subsequently facilitates the lung colonization of breast cancer cells." (PMID 32382015, 2020). "In patients with early HER2-positive breast cancer, CCL5 levels correlate with ERK phosphorylation, worse disease-free survival, and overall survival." (PMID 32630699, 2020). "Some researche had demonstrated that CCL5 promotes the development of malignant tumors including lung cancer, colorectal cancer, esophageal cancer, breast cancer and so on 12-15." (PMID 33173412, 2020). "In breast cancer, CCL5 secreted by MSCs of the TME increases tumor cell motility and invasion or recruits tumor cells in distant organs, facilitating their dissemination." (PMID 32630699, 2020). "CCL5 is secreted by breast cancer cells, leukocyte infiltrates near tumors, and by non-malignant stromal cells at the primary tumor site or sites of metastasis." (PMID 32630699, 2020). "There is a known linearized matrix in breast cancer, which we have seen in vitro is formed chiefly by fibroblasts under CCL5 signaling." (PMID 32252260, 2020). "We were able to validate multiple correlations with DEK expression and both down- and up-regulated genes in primary human breast cancers, including CCL5, CDC45, CDH1, and HDAC7." (PMID 32708944, 2020). "Silencing host CCL5 in bone marrow, in combination with maraviroc, had robust anti-tumor immunity effects and great therapeutic efficacy against breast cancer xenografts." (PMID 32630699, 2020). "TAM infiltration is associated with the expression of the chemoattractants CCL2 and CCL5, which are influenced by E2 in breast cancer." (PMID 32133288, 2020). "The expression of CCL5 in breast cancer cells promotes the proliferation and invasion of breast cancer cells through an autocrine pathway." (PMID 32081834, 2020). "This profile confirmed our previous results about the involvement of C-C motif chemokine ligand 5 (CCL5)/C-C motif chemokine receptor 5 (CCR5) in acquired resistance to trastuzumab in HER2-positive breast cancer (article in press)." (PMID 32365528, 2020). "CCL5 and tumor‐derived colony‐stimulating factor work together to promote the production of MDSCs in bone marrow, which helps to maintain the growth of breast cancer." (PMID 32253815, 2020). "High expression of CCR5 and its cognate ligands (CCL4, CCL5) in breast cancer promote tumor progression." (PMID 32253815, 2020).
breast cancer (continued). "Macrophages in this cluster express CCL5, a cytokine that has previously been associated with promotion of residual HER2+ breast cancer survival following HER2-targeted therapy." (PMID 32822576, 2020). "CCL5 acts as a reciprocal signal to the breast cancer cells to enhance their motility, invasion, and lung metastasis." (PMID 33333727, 2020). "The presence of CCL5 in biopsy samples has been reported as a prognostic indicator for stage II breast cancer progression." (PMID 32252260, 2020). "Zoledronic acid affects the secretion of CCL5 and IL-6 by MSCs, decreasing their effects on breast cancer cells." (PMID 32630699, 2020). "Studies had revealed that CCL5 promoted tumor migration and invasion through recruiting M2 type macrophages (TAMs) in breast cancer." (PMID 33173412, 2020). "By analyzing gene expression datasets from breast cancer patients treated with neoadjuvant targeted or chemotherapy, we show here that CCL5 expression is elevated in residual tumor cells that survive therapy." (PMID 30990165, 2019). "Our findings suggest that within the tumor microenvironment, CD9 is responsible for the crosstalk between BMMSCs and HCC1806 breast cancer cells (via CCL5, CCR5, and CXCR12) which contributes to chemoresistance." (PMID 31191817, 2019). "Beyond this, they established for the first time an inverse correlation between RKIP and CCL5 expression levels in clinical human breast cancer samples." (PMID 31766768, 2019). "Several investigations also emphasized IL6, IL8, CCL2, and CCL5 as stimulators of the survival, proliferation, and invasion of breast cancer cells." (PMID 31398937, 2019). "The size effect of CCL5 rs2107538 was higher in patients with TNBC than that observed in all patients with breast cancer." (PMID 31921621, 2019). "High levels of CCL5 expression predict a better survival in breast cancer patients (all subtypes included)." (PMID 31921621, 2019). "In our analysis, CCL5 was significant up-regulated in luminal B breast cancer tumor tissues, which indicated the key role of CCL5 in luminal B breast cancer." (PMID 31795964, 2019). "Recent years, the chemokine C-C motif ligand 5 (CCL5), also known as RANTES, is a member of the CC subfamily, has been associated with aggressive breast cancer." (PMID 31795964, 2019). "CCL5 expression is indeed associated with accumulation of CD8+ infiltrating T cells and associated with a favorable prognosis in colon cancer and breast cancer." (PMID 31921621, 2019). "CCL5 can be produced by various cells, such as breast cancer cells and mesenchymal stem cells, and is highly expressed in breast cancer tissue." (PMID 31500658, 2019). "ER- breast cancer has been correlated with increased NF-κB activity and increased expression of certain cytokines (IL-6, IL-8) and chemokines (CCL5, MCP-1 [CCL2])." (PMID 30736340, 2019). "The experiments also revealed that CCL5 levels were high in residual breast cancer tumors collected from women." (PMID 30990165, 2019). "In order to identify a specific association between certain CCL5 signaling pathways and TNBC, we stratified the 544 patients with breast cancer according to the breast cancer subtype, namely TNBC and hormone receptor positive breast cancer (HRBC)." (PMID 31921621, 2019). "The mRNA and protein expression of both CCL2 and CCL5 by IFN-γ activated breast cancer cells were significantly reduced in a dose-dependent manner by ZA treatment." (PMID 30808421, 2019). "In return, TAM-derived CCL5 induces breast cancer cell migration, EMT, and promotes aerobic glycolysis via AMPK signaling activation, resulting in increased metastatic ability." (PMID 30154786, 2018). "It is well established that CC motif chemokine ligand 5 (CCL5), also called RANTES, from mesenchymal stem cells and CCL18 from tumor-associated macrophages act on breast cancer cells to enhance cancer motility, invasion and metastasis." (PMID 30177620, 2018).
breast cancer (continued). "In ER- breast cancer, tumor-infiltrating FOXP3+ lymphocytes and CCL5 expression were associated to a good outcome." (PMID 29559701, 2018). "It has been reported that when Ezrin was silenced, CCL5 induced cell motility and invasiveness was also inhibited indicating the potential role for Ezrin in the process of CCL5 induced breast cancer cell metastasis." (PMID 30224826, 2018). "Breast cancer cells stimulated de novo secretion of the chemokine CCL5 from mesenchymal stem cells, which then acted in a paracrine fashion on the cancer cells to enhance their motility, invasion, and metastasis." (PMID 29772686, 2018). "A recent report demonstrates that the axis CCL5/CCR5 play a key role in a metabolic feedback loop between breast cancer cells and macrophages with important outcomes on immune system infiltrate." (PMID 30154786, 2018). "Analysis of transcriptome data sets from TCGA (The cancer genome atlas) using Oncomine and cBioPortal, confirmed the inverse correlation between BRCA1 and CCL5/ Moesin in breast cancer." (PMID 30224826, 2018). "Addition of anti-CCL5 neutralizing antibody to the co-culture system, not only inhibited breast cancer lung metastasis, but also decreased the expressions of CCR5, HK2 and p-AMPK." (PMID 29299159, 2017). "In the breast cancer microenvironment, cancer cell stimulate de novo secretion of CCL5 from MSCs, and CCL5 acts in a paracrine fashion to enhance cancer cell migration, invasion and metastasis." (PMID 29088737, 2017). "Anti-CCL5 neutralizing antibody significantly inhibited cell migration induced by lactate-activated THP-1 macrophages, suggesting that CCL5 was responsible for breast cancer cell migration induced by lactate-activated macrophages." (PMID 29299159, 2017). "Specifically, CCL5 levels are markedly higher in more aggressive forms of breast cancer and are predictive of rapid disease progression in stage II breast cancer patients." (PMID 29216863, 2017). "Paracrine CCL20 has been shown to induce epithelial-mesenchymal transition in breast cancer and CCL5 has been shown to promote vascular endothelial growth factor VEGF-induced angiogenesis." (PMID 29215599, 2017). "Production and release of CCL5 by MSC has been suggested to activate corresponding receptors such as CCR5 on adjacent breast cancer cells thereby promoting altered breast cancer development and metastasis." (PMID 28148265, 2017). "We provided evidence that CCL5 activation of CCR5 can stimulate proliferation of breast cancer cells in an mTOR-dependent manner." (PMID 29216863, 2017). "We demonstrated that TAMs under the stimulation of lactate produced large sums of CCL5, which facilitated breast cancer glycolysis and EMT." (PMID 29299159, 2017). "In this study, we found that cancer cell derived-lactate increased the secretion of CCL5 through Notch signaling in tumor-associated macrophages, and CCL5 in turn induced EMT and aerobic glycolysis in breast cancer cells." (PMID 29299159, 2017). "It has been demonstrated that the release of CCL5 by cells of the tumor microenvironment promotes the liver metastasis of breast cancer cells." (PMID 29088737, 2017). "High levels of both IL-6 and of CCL5 correlate with bad prognosis and an advanced metastatic stage in prostate and breast cancer." (PMID 28477013, 2017). "Highly expressed in various tumors, CCL5 promotes tumor growth and metastasis by inducing tumor cell proliferation, angiogenesis and matrix metallo-proteinases in breast cancer." (PMID 29371976, 2017). "It has previously been demonstrated that fibroblastic cells within the tumour stroma possess mesenchymal stem cell (MSC) qualities and that breast cancer cells stimulate secretion of CCL5, which in turn facilitates its metastatic capacity." (PMID 28372546, 2017). "The breast cancer cells promoted MSC secretion of chemokine CCL5, which acted in a paracrine fashion to increase cancer cell motility, invasion, and metastasis." (PMID 29088907, 2017).
breast cancer (continued). "Increased breast cancer cell metastatic capability was reversible and dependent on CCL5 signaling through the chemokine receptor, CCR5." (PMID 29088907, 2017). "CCL5 is a potent chemokine operative in several types of cancers, including lymphoma, melanoma, prostate cancer and breast cancer." (PMID 28380429, 2017). "For example, it has been shown that breast cancer cellscan stimulate the MSCs within the tumor stroma to produce a chemokine C–Cmotif chemokine ligand 5 (CCL5)." (PMID 28659496, 2017). "A variety of human cancers, including breast cancer, ovarian cancer, Hodgkin's lymphoma and prostate cancer, can secret CCL5 or express its receptor, CCR5." (PMID 29299159, 2017). "We further explored the linkage between CCL5-CCR5 axis and AMPK and found that CCL5 induced the phosphorylation of AMPK in breast cancer cells." (PMID 29299159, 2017). "As cancer usually prefers to aerobic glycolysis and produces high levels of lactic acid, these results suggested a possible correlation of lactate, TAMs and CCL5 in breast cancer." (PMID 29299159, 2017). "Further strengthening these results, studies were published demonstrating the secretion of CCL5 by in vitro by human bone marrow derived MSCs in response to osteosarcoma cells and breast cancer cells." (PMID 28148268, 2017). "In a breast cancer murine model, those murine cells treated with Met-CCL5 (receptor antagonist) had a decreased number of infiltrating macrophages associated with a significantly reduced tumor size." (PMID 26790618, 2016). "At the outset, we examined the effects of CCL5 treatment of the different breast cancer cell types on glucose uptake." (PMID 27335323, 2016). "Using metabolomics, we demonstrate that the metabolic signature of CCL5-treated primary mouse mammary tumour cells reflects increased anabolic metabolism." (PMID 27335323, 2016). "In a first series of experiments, we examined the effects of CCL5 on activation of the AKT/mTOR pathway in MDA-MB-231 human breast cancer cells." (PMID 27335323, 2016). "Breast cancer cells stimulate CCL5 secretion from MSC, which then acts in a paracrine fashion on the CCR5+ cancer cells to enhance their motility, invasion and metastasis." (PMID 27136535, 2016). "Of the signals downregulated in collagen -dense mammary tumors, CCL5 is the chemokine that has the greatest differential expression in WT mammary tumors." (PMID 27169366, 2016). "Next, to investigate the paracrine mechanism that cancer cell CCL5 operates to promote angiogenesis, we orthotopically implanted breast cancer cells into mice, which were homozygous null for either CCR1 or CCR5." (PMID 27863423, 2016). "Given that GLUT-1 expression is upregulated by AKT activation and we have shown CCL5 activation of AKT, we examined the effects of CCL5 treatment on GLUT-1 cell surface expression for the different breast cancer cells." (PMID 27335323, 2016). "Herein, using suppression of CCL5 in two immune competent murine breast cancer models, we demonstrate a paracrine role for cancer cell CCL5 in tumor neovascularization and growth." (PMID 27863423, 2016). "In agreement, we demonstrate that CCL5 treatment increases glucose uptake by breast cancer cells, mediated by CCR5 and mTOR-dependent." (PMID 27335323, 2016). "Such CCL5 signaling among further stimuli resulted in acceleration of migratory, invasive and metastatic capacity of the breast cancer cells." (PMID 27608835, 2016). "We found that CCL5 treatment increased extracellular acidification, a readout for glycolytic flux, and also increased the glycolytic capacity of breast cancer cells." (PMID 27335323, 2016). "We have now shown that CCL5 is needed for breast cancer cell motility and invasion promoted by adipocytes." (PMID 27027351, 2016).